NDUFAF2 (NADH:ubiquinone oxidoreductase complex assembly factor 2)
Description:
Acts as a molecular chaperone for mitochondrial complex I assembly. Complex I functions in the transfer of electrons from NADH to the respiratory chain. The immediate electron acceptor for the enzyme is believed to be ubiquinone. Is involved in the initial steps of cilia formation, including removal of CP110 from the mother centrioles, docking of membrane vesicles to the mother centrioles, and establishment of the transition zone.
Synonyms: B17.2L; MMTN; NDUFA12L; mimitin; MC1DN10
Tractability: Small molecule: an approved drug acts on it. PROTAC: ubiquitination databases record sites on it; its protein half-life has been measured.
Target class: Enzyme; Oxidoreductase
Gene: Protein-coding gene on chromosome 5 (60,945,177 to 61,154,531, forward strand). Ensembl gene ENSG00000164182.
Subcellular location: Mitochondrion
Subcellular location (Human Protein Atlas): Mitochondria
Pathways (Reactome):
Metabolism: Complex I biogenesis
Gene Ontology:
Molecular function: protein binding; protein-containing complex binding
Biological process: cilium assembly; mitochondrial respiratory chain complex I assembly
Cellular component: mitochondrion; mitochondrial inner membrane; membrane; respiratory chain complex I
Genetic constraint (gnomAD): Loss-of-function variants: 8 observed, 13.03 expected, observed/expected ratio (o/e) 0.61, 90% interval 0.36 to 1.11. The upper end of that interval is the gene's LOEUF score, 1.11, which puts it in group 4 of 6, group 1 being the genes least tolerant of losing a copy. Missense variants: 108 observed, 129.95 expected, observed/expected ratio (o/e) 0.83, 90% interval 0.71 to 0.98. Synonymous variants: 40 observed, 46.63 expected, observed/expected ratio (o/e) 0.86, 90% interval 0.67 to 1.12.
Gene-disease validity (ClinGen):
ClinGen rates the evidence that NDUFAF2 causes each of these diseases.
Leigh syndrome (autosomal recessive): Definitive. A progressive neurological disease defined by specific neuropathological features associating brainstem and basal ganglia lesions.
mitochondrial disease (autosomal recessive): Definitive.
Homologues: Orthologues: chimpanzee NDUFAF2 (100% identical), macaque NDUFAF2 (94% identical), rabbit NDUFAF2 (84% identical), mouse Ndufaf2 (80% identical), pig NDUFAF2 (80% identical), guinea pig NDUFAF2 (80% identical), dog NDUFAF2 (78% identical), rat Ndufaf2 (78% identical), zebrafish ndufaf2 (50% identical), tropical clawed frog ndufaf2 (49% identical), Drosophila melanogaster CG43346 (25% identical), Caenorhabditis elegans Y116A8C.30 (17% identical).
Diseases named in the same sentence as NDUFAF2 in open-access papers:
NDUFAF2 is named in the same sentence as 42 diseases in open-access papers, as found by Europe PMC text mining. Sharing a sentence is not in itself a finding about the gene and the disease. The quoted sentences say what the papers report.
Encephalopathy (3 papers, 2015 to 2025). Encephalopathy is a term that means brain disease, damage, or malfunction. "Pathogenic variants of NDUFAF2 are associated with mitochondrial complex I deficiency and nuclear type 10, characterized by episodic respiratory failure and encephalopathy, which matched the characteristics of our patient." (PMID 40709164, 2025). "Biallelic pathogenic variants in NDUFAF2, encoding the nuclear assembly CI factor NDUFAF2, were initially reported to cause progressive encephalopathy beginning in infancy." (PMID 38419071, 2024). "Intriguingly, ND1 protein deficiency does not totally preclude assembly of the holocomplex, similar to that observed in a patient with progressive encephalopathy due to a B17.2L (NDUFAF2) [MIM #609653] null mutation." (PMID 25626417, 2015).
Leigh syndrome (3 papers, 2012 to 2024). "Biallelic loss-of-function mutations in NDUFAF2 result in a distinctive phenotype in the spectrum of Leigh syndrome with clinical and neuroradiological features that are primarily attributed to progressive brainstem damage." (PMID 38419071, 2024). "Mutation in an intrinsic mitochondrial complex I component NDUFAF2 has been identified in Leigh syndrome, a severe inherited mitochondriopathy." (PMID 38949024, 2024). "Mitochondrial metabolism is linked to primary cilia signaling and ciliopathies via the Leigh syndrome–associated mitochondrial protein NDUFAF2." (PMID 38949024, 2024). "Defects in CI are the leading biochemical cause of Leigh syndrome and NDUFAF2, an established CI-assembly factor, is among the various genetic causes resulting in this syndrome." (PMID 38419071, 2024). "Pathogenic variants in NDUFAF2 result in a distinctive clinical and neuroradiological form of Leigh syndrome characterized by progressive brainstem disruption with early lethality." (PMID 38419071, 2024). "In patients with NDUFAF2 mutations, brainstem symptoms and Leigh syndrome on MRI were observed in all patients, as well as a high prevalence of pale optic discs or optic atrophy." (PMID 22644603, 2012). "In summary, NDUFAF2-associated Leigh syndrome has a distinctive neuroradiological course and progression that differ somewhat from the classical Leigh syndrome pattern with radiological lag compared with the clinical symptoms and inter individual variability even in patients with the same genotype." (PMID 38419071, 2024). "Biochemical studies are largely noninformative in NDUFAF2-associated Leigh syndrome." (PMID 38419071, 2024). "However, in clinical practice, OXPHOS activity is no longer required for a diagnosis of NDUFAF2-associated Leigh syndrome, and clinicians can rely on the typical clinical and neuroradiological phenotype associated with confirmatory NDUFAF2 loss-of-function variants." (PMID 38419071, 2024).
lung carcinoma (2 papers, 2023 to 2024). "Among them, a number of proteins related to mitochondrial biogenesis were upregulated in BrM lesions as compared to paired primary lung cancers, including NDUFAF2, SDHB, COX5A, and ATP5PO." (PMID 39593114, 2024). "Furthermore, the expression of NDUFAF2 was significantly higher in the lung cancer cell lines." (PMID 36703939, 2023).
Parkinsonism (2 papers, 2024 to 2025). Characteristic neurologic anomaly resulting from degeneration of dopamine-generating cells in the substantia nigra, a region of the midbrain, characterized clinically by shaking, rigidity, slowness of movement and difficulty with walking and gait. "The loss of function of NDUFAF2 could cause mitochondrial encephalopathy, and there are some cases of complex I-associated mutations resulting in Parkinsonism or substantia nigra pars compacta-selective neurodegeneration regulation." (PMID 38240717, 2024).
Progressive encephalopathy (2 papers, 2023 to 2024). "Biallelic pathogenic variants in the gene NDUFAF2, encoding the nuclear CI-assembly protein NDUFAF2, were initially reported to cause progressive encephalopathy beginning in infancy." (PMID 38419071, 2024). "The deficiency of NDUFAF2 due to null mutations does not absolutely restrain the assembly or activity of complex I, although it contributes to the development of a progressive encephalopathy." (PMID 36703939, 2023).
attention deficit-hyperactivity disorder (1 paper, 2012). A disorder characterized by a marked pattern of inattention and/or hyperactivity-impulsivity that is inconsistent with developmental level and clearly interferes with functioning in at least two settings (e.g. at home and at school). "Also, two patients (RM4073 and RM4285) had a 622 kb duplication on chr 5q12.1 affecting five genes, including the NDUFAF2 gene that encodes a chaperone for mitochondrial complex I assembly and that was found to be implicated in attention-deficit/hyperactivity disorder." (PMID 22384383, 2012).
Joubert syndrome (1 paper, 2024). Joubert syndrome (JS) is characterized by congenital malformation of the brainstem and agenesis or hypoplasia of the cerebellar vermis leading to an abnormal respiratory pattern, nystagmus, hypotonia, ataxia, and delay in achieving motor milestones. "Building on the observation that NDUFAF2 deficiency results in ciliary abnormalities, we investigated a Joubert syndrome family with a known mutation within ARMC9." (PMID 38949024, 2024). "Therefore, we concluded that ARMC9-deficient cells derived from a patient with Joubert syndrome exhibit mitochondrial defects, which can be rescued by NDUFAF2 expression." (PMID 38949024, 2024). "However, the exact mechanisms underlying the relationship between NDUFAF2 overexpression and autophagy inhibition in Joubert syndrome require further investigation." (PMID 38949024, 2024). "Importantly, we show that a patient with Joubert syndrome due to ARMC9 mutation had a decreased level of NDUFAF2 protein, deficient mitochondrial activity, and increased oxidative stress." (PMID 38949024, 2024). "NDUFAF2 rescues the mitochondrial defect and cilia formation in a patient with Joubert syndrome." (PMID 38949024, 2024).
lung adenocarcinoma (1 paper, 2023). A carcinoma that arises from the lung and is characterized by the presence of malignant glandular epithelial cells. "We speculated that NDUFAF2 mainly affects mitochondrial complex I to influence the progression of lung adenocarcinoma." (PMID 36703939, 2023). "However, whether NDUFAF2 plays a role in lung adenocarcinoma (LUAD) is largely unexplored." (PMID 36703939, 2023).
neuroblastoma (1 paper, 2017). Neuroblastoma (NB) is the most common solid, extracranial childhood tumor. "Furthermore, a recent report has highlighted the contribution of Ndufaf2 in OS and DNA damage: deficiency in this gene increased mitochondrial ROS and mtDNA deletions in a human knockdown neuroblastoma cell line as well as in mouse knockout fibroblasts." (PMID 27819115, 2017).
neuropathy (1 paper, 2021). A disorder affecting the nervous system that manifests with pain, tingling, numbness, and/or muscle weakness. "The presence of neuropathy in our cohorts is associated with variants in the ELOVL7 and NDUFAF2 genes that are located in the same region on chromosome 5." (PMID 33935957, 2021). "SNP rs2694528 in NDUFAF2, which is near ELOVL7, is associated with the presence of neuropathy." (PMID 33935957, 2021).
type 2 diabetes mellitus (1 paper, 2021). A type of diabetes mellitus that is characterized by insulin resistance or desensitization and increased blood glucose levels. "NDUFAF2 encodes a subunit of a target of metformin, an approved medication for type 2 diabetes mellitus." (PMID 34930919, 2021).
tumor (2 papers, 2013 to 2023). "To clarify the association of NDUFAF2 expression level with tumor immune response, we further performed an enrichment analysis of the LUAD TME using ssGSEA." (PMID 36703939, 2023). "Abnormality of NDUFAF2 such as mutations causes mitochondrial complex I deficiency, mitochondrial complex I is very important in tumor metabolism, and defective NADPH production in mitochondrial disease complex I leads to inflammation and cell death." (PMID 36703939, 2023). "Simultaneously, the proportions of various tumor-infiltrating immune cells (TIICs) in different TMEs were adopted to explore the correlation between NDUFAF2 and TIICs according to CIBERSORT." (PMID 36703939, 2023). "Furthermore, upregulation of NDUFAF2 in LUAD was positively correlated with tumor immune infiltration of DC and Th2 cells." (PMID 36703939, 2023). "Through the analysis of multiomics outcome from LUAD samples, we reported that the level of NDUFAF2 in the tumor tissues is higher than that in adjacent nontumor tissues." (PMID 36703939, 2023). "To identify the expression pattern of NDUFAF2 at the mRNA level in tumor and nontumor lung tissues, we analyzed the expression level of NDUFAF2 in various tumors and normal tissues using TCGA database." (PMID 36703939, 2023). "IMR90 cells, on the other hand, seemed to be impacted by a different panel of genes, BTG2, FBXW7, NDUFAF2, PHLDA1, and DMD, whose knockdown did not have a significant impact in the two tumor cell lines, suggesting cell line-specific effects." (PMID 24009623, 2013).
cancer (1 paper, 2023). A tumor composed of atypical neoplastic, often pleomorphic cells that invade other tissues. "NDUFAF2 might play a key role in cancer cell proliferation, which could be used as a new independent prognostic marker, and its expression level was correlated with immune infiltrates in LUAD." (PMID 36703939, 2023).
NDUFAF2 also shares sentences with these, for which no sentence is quoted: optic atrophy (2 papers); acute myeloid leukemia (1); asthma (1); bladder urothelial carcinoma (1); cardiomyopathies (1); cervical squamous cell carcinoma (1); cholangiocarcinoma (1); ciliopathies (1); diffuse large B-cell lymphoma (1); esophageal carcinoma (1); glioblastoma multiforme (1); kidney chromophobe carcinoma (1); low grade glioma (1); maple syrup urine disease (1); mitochondrial disease (1); Mitochondrial encephalopathy (1); nephronophthisis (1); Nystagmus (1); Oral ulcer (1); ovarian serous cystadenocarcinoma (1); prostate adenocarcinoma (1); rectal adenocarcinoma (1); respiratory failure (1); skin cutaneous melanoma (1); stomach adenocarcinoma (1); tauopathies (1); testicular germ cell tumor (1); thymoma (1); thyroid carcinoma (1).